TRPV2 (transient receptor potential cation channel subfamily V member 2)
Diseases named in the same sentence as TRPV2 in open-access papers (continued):
Sharing a sentence is not in itself a finding about the gene and the disease.
glioblastoma (continued). "After using CBD to stimulate TRPV2 expression and activity in glioblastoma stem cells, a reduction in stem cell proliferation and self-renewal properties was detected, correlating with an increase in the terminal differentiation marker, GFAP, and a decrease in the stem cell markers CD133 and Oct-4." (PMID 36142596, 2022). "The activation of TRPV2 through CBD has also been shown to induce apoptosis in glioblastoma cells without causing any considerable cytotoxicity on normal astrocytes." (PMID 35267489, 2022). "On the other hand, in glioblastoma cells, stimulation of TRPV2 could sensitize cancer cells to cytotoxic chemotherapeutic agents." (PMID 34356643, 2021). "Piperlongumine selectively inhibits human TRPV2 (IC50 = 4.6 μM) and reduces tumor sizes when applied to a murine glioblastoma model." (PMID 41118703, 2025). "Finally, using a patient cohort, we defined a significant TRPV2 interactome-based signature for the prognosis of an important brain disease, such as glioblastoma multiforme (GBM) and we validated the defined signature in two independent cohorts." (PMID 29719613, 2018). "In glioblastoma, CBD increased the plasma membrane expression of TRPV2 and prevented cell resistance to carmustine (BCNU), doxorubicin, and temozolmide." (PMID 29066974, 2017). "All the evidence points to negative control of the survival and proliferation of glioblastoma (GBM) by TRPV2." (PMID 33376561, 2020). "Furthermore, in vitro studies in glioblastoma cells demonstrated enhanced radiosensitivity with TRPC6 inhibition, while activation of TRPV2 channel increased chemosensitivity of cells." (PMID 30691160, 2019). "TRPV2 is overexpressed in GBM and it has been shown that its activation by cannabidiol sensitizes GBM cells to chemotherapeutics and also inhibits proliferation of Glioblastoma stem-cell like cells." (PMID 29719613, 2018). "By contrast, TRPV2 is reduced in glioblastoma multiforme (GBM) compared to normal astrocytes." (PMID 32887395, 2020).
hepatocellular carcinoma (22 papers, 2018 to 2025). A malignant tumor that arises from hepatocytes. "Taken together, these findings imply that a combination of TRPV1 and TRPV2 immunostains may separate low risk (TRPV1+/TRPV2−) and high-risk (TRPV1−/TRPV2+) hepatocellular carcinoma patients." (PMID 37240443, 2023). "Conversely, TRPV2 elimination substantially upregulates cancer stem cell markers while enhancing spheroid and hepatoma colony formation in human hepatoma HEpG2 cells." (PMID 41397955, 2025). "CALB2 has been proposed to promote hepatocellular carcinoma metastasis via the TRPV2-Ca2+-ERK1/2 signaling pathway." (PMID 39358777, 2024). "CBD promotes doxorubicin uptake in hepatocellular carcinoma (BNL1) cells by activating the TRPV2 channel, thereby facilitating doxorubicin-mediated cell death." (PMID 38397045, 2024). "CBD enhances the action of doxorubicin in hepatocellular carcinoma by promoting doxorubicin entry into cancer cells through TRPV2 and inhibiting P-glycoprotein ATPase transporter to reduce doxorubicin clearance." (PMID 38397045, 2024). "In this study, 29% of hepatocellular carcinoma cases showed high TRPV2 protein expression; these were predominantly poorly differentiated cancers with evidence of portal vein invasion." (PMID 37240443, 2023). "In vitro and in vivo studies have shown that CALB2 promotes hepatocellular carcinoma metastasis via the TRPV2-Ca2+-ERK1/2 signaling pathway." (PMID 35836930, 2022). "Increased blood glucose in diabetes induces oxidative stress in cells, and ROS has been reported to increase the expression of TRPV2, which mediates cell death in human hepatoma cells." (PMID 35406761, 2022). "Over-expression of TRPV2 in H2O2-treated hepatocellular carcinoma cells exacerbated the inhibition of AKT and Nrf2, whereas the activation of p38 and JNK has been enhanced at the early stage of cell death." (PMID 36033489, 2022). "TRPV2 involvement in human hepatocarcinogenesis was inferred from the observation that TRPV2 expression at mRNA and protein levels is increased in moderately and well-differentiated hepatocellular carcinoma tissues compared to poorly differentiated tumors." (PMID 33376561, 2020). "And it could significantly enhance the cytotoxicity of H2O2-mediated oxidative stress, suggesting up-regulated TRPV2 attenuated oxidative adaptation in hepatocellular carcinoma cells." (PMID 36033489, 2022). "Over-expression of TRPV2 can attenuate the stemness of hepatoma SMMC-7721 cells." (PMID 35887116, 2022). "TRPV2 has been found up-regulated in human hepatocellular carcinoma cells." (PMID 36033489, 2022). "In hepatoma and hepatocarcinoma models, TRPV2 may also increase drug resistance and suppression of TRPV2 activity in nude mice xenografts reduced tumor growth and invasion." (PMID 34356643, 2021). "In the human hepatocellular carcinoma cell lines HepG2 and Huh-7, TRPV2 was found to mediate H2O2-induced oxidative stress and cell death by potentiating the inhibition of the prosurvival signaling proteins (Akt, Nrf2) and enhancing prodeath signaling proteins (p38, JNK1)." (PMID 33376561, 2020). "However, it is noteworthy that, in order to retain normalization of the liver and heart cells, we used here normal liver and heart tissue and compared the TRPV2 expression between cell line (hepatocellular carcinoma) and these tissues." (PMID 31680972, 2019). "First, we examined whether BNL1 ME cells overexpress TRPV2 similarly to previous reports of hepatocellular carcinoma cells." (PMID 31680972, 2019). "Here, we sought to examine whether a pore of TRPV2 channels expressed by a murine model of hepatocellular carcinoma cells [BNL1 ME] could be used to shuttle doxorubicin into these cells selectively." (PMID 31680972, 2019). "TRPC6 and TRPV2 may contribute to the progression of hepatocellular carcinoma, which may be related to the stemness of hepatocellular carcinoma, migration, and the invasion of hepatocellular carcinoma cells." (PMID 38255767, 2024).
hepatocellular carcinoma (continued). "Notably, reduction of TRPV2 mRNA and protein expression levels in poorly differentiated tumors in comparison to higher differentiated hepatoma supports the idea that reduced TRPV2 expression promotes the stem cell features of hepatoma cells during the early stages of tumor development." (PMID 33376561, 2020). "Therefore, TRPV2 was proposed to be a potential target in hepatoma therapy." (PMID 32182937, 2020). "Notably, reduced expression of TRPV2 mRNA and protein in poorly differentiated tumors in comparison to higher differentiated hepatoma supports the idea that reduced TRPV2 expression promotes the stem-cell features of hepatoma cells during the early stages of tumor development." (PMID 32182937, 2020). "In human hepatocellular carcinoma (HCC), TRPV2 expression was found in increased levels at both mRNA and protein levels, and its high expression inhibited tumor differentiation." (PMID 35558077, 2022). "Recent studies have shown that TRPV2 promotes H2O2-induced oxidative stress and cytotoxicity in human hepatoma cells." (PMID 35267489, 2022). "In contrast, knockout of TRPV2 can significantly increase cancer stem cell markers (CD133, CD44, and ALDH1) and enhance spheroid and colony formation in human hepatoma HepG2 cells." (PMID 35887116, 2022). "A recent study also showed that TRPV2 promotes H2O2-induced oxidative stress and cytotoxicity in human hepatoma cells." (PMID 30323891, 2018). "Notably, the downregulation of TRPV2 has been observed to significantly enhance the colony-forming capacity of HepG2 cells and the expression of stem cell markers CD133 and CD44 in hepatoma cell lines." (PMID 37569884, 2023). "Moreover, in human hepatoma cell line SMMC-7721, which exhibits lower TRPV2 protein expression than HepG2, reinforced TRPV2 expression led to the reduction of the expression of LCSLCs markers and reduced spheroid and colony formation." (PMID 32182937, 2020). "Similar findings were also observed in hepatocellular carcinoma in which TRPV2 activation by CBD or 2-APB (Aminoethoxydiphenyl borate) was found to improve DOXO permeation into tumor cells, thus corroborating an intriguing role of TRPV2 in increasing tumor cell sensitivity to chemotherapy drugs." (PMID 33928077, 2021). "Here, we show that, differently from non-cancerous liver and heart cells, mouse hepatocellular carcinoma BNL1 ME cells express a large-pore cationic channel receptor, TRPV2." (PMID 31680972, 2019).
breast carcinoma (21 papers, 2016 to 2025). "In this study, we found high levels of TRPV2 expression associated with advanced malignancy, thereby suggesting its potential as a biomarker for breast cancer staging." (PMID 39334351, 2024). "The mechanisms underlying the translocation of TRPV2 from the ER to the cell membrane in breast cancer cells remain elusive." (PMID 39334351, 2024). "We have previously shown that the promigratory activity of LL-37 in breast cancer cell lines is linked to the activation of the TRPV2 Ca-channel and influx of extracellular calcium." (PMID 31547381, 2019). "In invasive breast cancer cells, the TRPV2 agonist CBD inhibits ERK-dependent breast cancer proliferation through sustained upregulation of ERK activity." (PMID 40078961, 2025). "US stimulation not only promotes ion release from BG but also activates the TRPV2 channel, disrupting calcium homeostasis in breast cancer cells, inducing mitochondrial autophagy, and ultimately triggering apoptosis." (PMID 40013983, 2025). "TRPV2 is aberrantly expressed in almost all breast cancers, and TRPV2 also serves as a valuable biomarker and a promising candidate target for therapeutic intervention." (PMID 40078961, 2025). "Here, a dual‐gating strategy combining locally delivered borate glass (BG) and ultrasound (US) is developed for the precise and effective inhibition of breast cancer by targeting transient receptor potential vanilloid 2 (TRPV2)." (PMID 40013983, 2025). "Collectively, these findings suggest that the activation of TRPV2 promotes breast cancer progression." (PMID 39334351, 2024). "Collectively, these findings support the oncogenic role of TRPV2 in the growth and metastasis of breast cancer." (PMID 39334351, 2024). "To further elucidate the role of TRPV2 in breast cancer, we utilized a knockdown strategy both in vitro and in vivo." (PMID 39334351, 2024). "Our findings demonstrated a significant reduction in TRPV2 mRNA levels in breast cancer cells (MCF-7, SK-BR-3, and MDA-MB-231) transfected with TRPV2 siRNA." (PMID 39334351, 2024). "To investigate the role of TRPV2 in breast cancer cells, we employed a small interfering RNA (siRNA) targeting TRPV2 (SiTRPV2) in MCF-7, SK-BR-3, and MDA-MB-231 cell lines." (PMID 39334351, 2024). "Collectively, these findings suggest that TRPV2 promotes the progression of breast cancer by upregulating autophagy." (PMID 39334351, 2024). "Collectively, these findings imply a potential involvement of TRPV2 in the progression of breast cancer, suggesting a significant role of TRPV2 in the disease advancement." (PMID 39334351, 2024). "RT-PCR analysis revealed an overexpression of TRPV2 in the breast cancer cell lines compared to normal breast cells." (PMID 39334351, 2024). "We demonstrated that TRPV2 activation promotes breast cancer cell proliferation, migration, and invasion, while silencing of TRPV2 suppresses breast cancer progression, highlighting the oncogenic role of TRPV2." (PMID 39334351, 2024). "While these studies suggest the potential of targeting TRPV2 as a therapeutic approach in cancer treatment, its role in breast cancer progression remains largely unexplored." (PMID 39334351, 2024). "To corroborate our findings using a gain-of-function approach, we further introduced stable overexpression of the TRPV2 channel in MDA-MB-231 breast cancer cells (OE TRPV2) in xenograft tumor model." (PMID 39334351, 2024). "Consistent with our observations for AMPK expression, knockdown of TRPV2 in breast cancer cells resulted in inhibition of ULK1 phosphorylation at serine 555, while cannabidiol treatment led to upregulation of ULK1 phosphorylation." (PMID 39334351, 2024). "These investigations hold the potential to uncover novel therapeutic targets for upstream interventions aimed at modulating TRPV2-mediated functions in breast cancer." (PMID 39334351, 2024). "Taken together, these findings provide evidence that TRPV2 modulates autophagy in breast cancer through the CaMKKβ-AMPK-ULK1 cascade." (PMID 39334351, 2024).
breast carcinoma (continued). "To accomplish this, we employed cannabidiol as a pharmacological tool to activate TRPV2 in breast cancer cells, and extra Fluo-4 labeled calcium buffer were applied to monitor and track the dynamic changes in calcium levels within the cellular context." (PMID 39334351, 2024). "Our findings revealed a significant reduction of CaMKKβ in breast cancer cells upon TRPV2 silencing, while TRPV2 activation with cannabidiol treatment led to increased phosphorylation of CaMKKβ." (PMID 39334351, 2024). "Consistently, western blot analysis further revealed decreased expression of ATG, a reduced ratio of LC3-II to LC3-I, and increased SQSTM1 in breast cancer cells with TRPV2 knockdown." (PMID 39334351, 2024). "Our findings demonstrate that TRPV2 actively promotes breast cancer progression by activating autophagy, offering a novel avenue for the development of therapeutic interventions in breast cancer treatment by specifically targeting TRPV2." (PMID 39334351, 2024). "In light of the demonstrated modulatory role of TRPV2 in breast cancer, we proceeded to investigate the potential dependency of TRPV2-mediated regulatory effects on autophagy." (PMID 39334351, 2024). "To further validate our findings, we conducted IHC staining to examine TRPV2 expression in breast cancer tissues obtained from patients." (PMID 39334351, 2024). "Our study provides evidence showcasing the high expression of TRPV2 in advanced stages of breast cancer, underscoring its potential as a biomarker for advanced disease." (PMID 39334351, 2024). "Our data revealed that TRPV2 exerts a promotional effect on breast cancer cell invasion, as evidenced by a significant reduction in the number of invaded cells upon TRPV2 silencing." (PMID 39334351, 2024). "Subsequently, we employed transwell assay to investigate the impact of TRPV2 on the invasion of breast cancer cells in vitro." (PMID 39334351, 2024). "TRPV2 has the potential to serve as a novel biomarker for patients with triple-negative breast cancer and basal-type breast cancer." (PMID 37755210, 2023). "As mentioned in the review, the activation of the TRPV2 by its cannabidiol increases the cellular uptake of doxorubicin, which enhances the sensitivity of breast cancer cells to chemotherapy in vitro and in vivo." (PMID 37755210, 2023). "The prognostic value of TRPV2 has been revealed in certain cancers, including gastric cancer, breast cancer, and endometrial cancer." (PMID 35140788, 2022). "SDC4 is a receptor for LL-37 increasing Ca2+ levels via TRPV2 channels and increasing the motility of breast cancer cells via PI3K/AKT signaling." (PMID 34282767, 2021). "In breast cancer cells, treatment with Rho-kinase inhibitors leads to a reduction in TRPV2 levels, indicating a Rho-dependent regulation of TRPV2 activity." (PMID 34356643, 2021). "In fact, TRPV2 activation with CBD enhanced the sensitivity of breast cancer cells towards the chemotherapeutic drug, resulting in greater inhibition of tumor growth in vitro and in vivo." (PMID 33376561, 2020). "Recently, it has been reported that TRPV2 should be considered a prognostic marker for triple negative and ERβ- breast cancer patients." (PMID 32751388, 2020). "In particular, tranilast was reported to block IGF-1-induced cell growth of the low TRPV2-expressing breast cancer cell line MCF-7 by blocking calcium influx mediated by a voltage-independent calcium-permeable channel." (PMID 33376561, 2020). "On breast cancer cell lines, LL-37 increases intracellular calcium via the TRPV2 channel and their migration via the activation of PI3K/AKT signaling." (PMID 31547381, 2019). "We found that ERα- breast cancer patients who express higher level of TRPV2 have significantly higher RFS than patients with lower TRPV2 expression level." (PMID 30323891, 2018).